BCL11A (BCL11 transcription factor A)
Diseases named in the same sentence as BCL11A in open-access papers (continued):
Sharing a sentence is not in itself a finding about the gene and the disease.
acute promyelocytic leukemia (2 papers, 2013 to 2025). An aggressive form of acute myeloid leukemia (AML), characterized by arrest of leukocyte differentiation at the promyelocyte stage, due to a specific chromosomal translocation t(15;17) in myeloid cells. "However, studies have shown that acute promyelocytic leukemia is induced by the downregulation of BCL11A expression to inhibit myeloid differentiation, and its specific mechanism requires further study." (PMID 39857257, 2025).
asthma (2 papers, 2021 to 2022). "A GWAS of asthma symptoms in 1,246 children in the population of Salvador, Brazil, was carried out; they found that BCL11A is associated with hematopoietic symptoms of asthma, and it may be related to its interaction with BCL 6 and participation in hematopoietic cell differentiation." (PMID 35712670, 2022). "In addition, in another study of severe asthma, they found that BCL11A was downregulated." (PMID 35712670, 2022).
brain tumors (2 papers, 2012 to 2019). "TLX association with BCL11A might provide a new therapeutic approach for brain tumors." (PMID 22675500, 2012). "BCL11A is a key factor in brain development but little is known about BCL11A in brain tumors." (PMID 31654056, 2019). "Based on the yeast-two-hybrid screening of a human adult brain cDNA library, BCL11A was identified as a novel co-regulator of nuclear receptor subfamily 2 group E member 1 (TLX) and may associate with TLX-related functions, such as neural stem cells maintenance and brain tumors." (PMID 31654056, 2019).
diffuse large B-cell lymphoma (2 papers, 2013 to 2023). "In addition, studies on Burkitt lymphoma (EB1) cell lines and diffuse large B-cell lymphoma (SU-DHL-6) cell lines found that siRNA-mediated inhibition of BCL11A expression reduced cell viability and directed cells toward apoptosis." (PMID 37372998, 2023). "Additionally, the loss of expression of the BCL11A-XL isoform was a negative prognostic factor in NSCLC and diffuse large B-cell lymphomas (DLBCLs)." (PMID 37372998, 2023).
endometrial tumor (2 papers, 2019 to 2020). "From the endometrial tumor eQTL data, we found that the top eQTL for the HiChIP target gene BCL11A was rs7579014, a CV at the 2p16.1 risk locus." (PMID 31561579, 2019). "Three of these associations were observed in whole blood (SNX11, HOXB2 and SRP14) and one in endometrial tumors (BCL11A)." (PMID 31561579, 2019).
Hyperglycemia (2 papers, 2018 to 2019). An increased concentration of glucose in the blood. "One is ‘feed-forward’ mechanism, as a glucose-induced gene, high expression of BCL11A is triggered by initial hyperglycemia, increased BCL11A inhibits insulin secretion and causes severe hyperglycemia, which further enhance the expression of BCL11A and finally leads to T2D." (PMID 31654056, 2019). "Based on evidence that HbA1c elevation, indicating chronic hyperglycemia, was correlated with elevated islet BCL11A mRNA, we postulated that islet BCL11A expression might be regulated by glucose, an effect not previously reported." (PMID 30242153, 2018). "We suggest that hyperglycemia may initiate a “feed forward” sequence of elevated BCL11A expression leading to impaired insulin secretion and worsening hyperglycemia, like that seen in T2D patients." (PMID 30242153, 2018). "However, inappropriately reduced BCL11A expression could also result in a pathological sequence of chronic, relatively increased insulin secretion, leading to insulin resistance, beta cell exhaustion, and eventual hyperglycemia." (PMID 30242153, 2018).
liver cancer (2 papers, 2017 to 2022). An epithelial or non-epithelial malignant neoplasm that arises from the liver. "Within the regions prioritised by the combined score, we also identified several extremely highly conserved regions that are recurrently mutated in the LIRI-JP cohort (liver cancer), including non-coding regions of the genes BCL11A, BCL6, and PAX5." (PMID 28056774, 2017).
mental disorder (2 papers, 2025). A disease that has its basis in the disruption of mental process. "Furthermore, some of these genes (e.g., NEGR1, PTBP2, BCL11A, ARNTL, SLC25A12, ADARB1) were identified in a recent study investigating the genetic overlap between AN and mental disorders, further supporting their relevance to AN." (PMID 39971893, 2025).
Neurodevelopmental delay (2 papers, 2024). "In 2014, a patient with a microdeletion restricted to the BCL11A gene was described with neurodevelopmental delay, severe speech disorder, and attention deficit, thereby delineating these traits for the first time specifically to BCL11A." (PMID 38392344, 2024).
Abdominal obesity (1 paper, 2015). Excessive fat around the stomach and abdomen. "The reported T2D risk alleles of three SNPs, including the T allele of rs243021 near BCL11A, the G allele of the intronic rs10830963 in MTNR1B, and the C allele of the intronic rs2237895 in KCNQ1, contributed to a decreased risk for abdominal obesity in T2D patients." (PMID 26599349, 2015).
Alpha-thalassemia (1 paper, 2024). Alpha-thalassemia is an inherited hemoglobinopathy characterized by impaired synthesis of alpha-globin chains leading to a variable clinical picture depending on the number of affected alleles. "On the other hand, alpha-thalassemia protected patients against albuminuria and hyperfiltration, while BCL11A variants were protective against albuminuria alone." (PMID 38791464, 2024).
astrocytoma (1 paper, 2018). "However, no such report has confirmed the contribution of BCL11A on astrocytoma, validating that it may be a potential biomarker for the distinction of the three glioma subtypes." (PMID 30322114, 2018).
autonomic dysfunction (1 paper, 2025). "Features suggestive of autonomic dysfunction, reported in other neurodevelopmental syndromes, are newly identified manifestations of BCL11A-IDD." (PMID 39448799, 2025).
BAFopathy (1 paper, 2016). Disorder caused by mutations in the various subunits composing the BAF complex. "Together, our observations underscore the importance of BCL11A dosage in mammalian brain development and as a cause of a previously undescribed BAFopathy syndrome." (PMID 27453576, 2016).
blood disease (1 paper, 2025). A disease that occurs in the blood. "At the same time, the treatment of blood diseases targeting BCL11A may have other side effects." (PMID 39857257, 2025).
brain malformations (1 paper, 2025). "We compared the frequency of brain malformations in the combined dataset of BCL11A-IDD with that in patients reported with large contiguous gene deletions encompassing BCL11A." (PMID 39448799, 2025).
carpal tunnel syndrome (1 paper, 2026). Entrapment of the median nerve in the wrist that is characterized by numbness, tingling and painful movement. "These included associations with genes involved in neurotransmitter signaling (HTR3A), immune function (HLA-DQB1, BCL11A), extracellular matrix remodeling (COL11A1, ADAMTS17, LOXL4), axon guidance and neural development (DCC, ETV1, NEGR1), and carpal tunnel syndrome (DIRC3)." (PMID 41518141, 2026).
cortical dysplasia (1 paper, 2023). "Deletions affecting only the BCL11A gene are not penetrant for hearing loss and IUGR traits, while those uniquely involving the USP34 and XPO1 genes are neither penetrant for cortical dysplasia nor for cerebellar anomalies." (PMID 36807877, 2023).
epilepsy syndrome (1 paper, 2024). A syndrome that has a characteristic cluster of clinical features and/or lectroencephalographic (EEG) findings that reflect underlying epileptic activity. "Genetic variations of its paralog, BCL11A, have also been increasingly linked to epilepsy syndromes, including TLE." (PMID 38927072, 2024). "Similarly, pathogenic variants of BAF subunits Bcl11a und b induce intellectual disability disorders often associated with epileptic syndromes." (PMID 38927072, 2024).
erythroleukemia (1 paper, 2021). Acute erythroid leukemia characterised by the presence of at least 50% erythroid precursors and at least 20% myeloblasts in the bone marrow. "Interestingly, this C2HC zinc finger (ZnF0) has been suggested to be dispensable for HbF silencing by the XL isoform of BCL11A in mouse erythroleukemia cells." (PMID 34634037, 2021).
glioma (1 paper, 2018). A benign or malignant brain and spinal cord tumor that arises from glial cells (astrocytes, oligodendrocytes, ependymal cells). "The following two optimal genes, SPRY4 (rank 8) and BCL11A (rank 9), act differentially on the three glioma subtypes according to recent publications." (PMID 30322114, 2018).
hearing loss (1 paper, 2023). "For almost all traits, except IUGR and hearing loss, our analysis pinpointed at least two SROs including the BCL11A, and the USP34 and XPO1 genes, respectively." (PMID 36807877, 2023).
Hyperkeratosis (1 paper, 2021). Hyperkeratosis is a histopathological term defining a thickened stratum corneum and may be present in many different skin conditions, with many possible overlaps. "The overlapping DEGs included genes associated with hyperkeratosis (upregulated LCE3E and TMEM45A), wound healing (upregulated KRT17, IL36G, TNC, and TGFBI), barrier defects (downregulated FRAS1 and BCL11A), and response to infection (upregulated IL36G, ADAP2, DFNA5, RFTN1, LITAF, and TMEM173)." (PMID 34506598, 2021).
ichthyosis (1 paper, 2022). Disorders of cornification that are characterized by visible scaling and/or hyperkeratosis of most or all of the skin. "As was suggested in the prior section on ichthyosis, future studies of AD would also benefit from investigation of the role of BCL11A in AD pathogenesis." (PMID 35214050, 2022). "The gene BCL11A, also known as (COUP-TF)-interacting protein 1 (CTIP1), is one genetic factor that is currently being investigated because of its role in the pathogenesis of epidermal barrier defects associated with several inflammatory skin disorders, namely AD, ichthyosis, and psoriasis." (PMID 35214050, 2022).
ichthyosis vulgaris (1 paper, 2022). The most common form of ichthyosis. "The influence of genetic factor B-cell lymphoma/leukemia 11A (BCL11A) on skin barrier defects involved in AD and ichthyosis vulgaris is further expanded upon." (PMID 35214050, 2022).
language delay (1 paper, 2016). "All individuals that we identified with BCL11A mutations presented with global delay in developmental milestones, including speech and language delay." (PMID 27453576, 2016).
large cell carcinoma (1 paper, 2013). A malignant epithelial neoplasm composed of large, atypical cells. "Thus, BCL11A was amplified in SCC, while in large-cell carcinoma (LCC) (n = 11) the intensity was 0.23, indicating no BCL11A gene amplification." (PMID 23758992, 2013).
medullary carcinomas (1 paper, 2023). "Furthermore, BCL11A was overexpressed in more aggressive histologic types, such as metaplastic and medullary carcinomas." (PMID 36030436, 2023).
metastasis (1 paper, 2017). The spread or migration of cancer cells from one part of the body (where they first appeared) to another. "Some studies observed that the BCL11A-high-expression patients were more frequently diagnosed in the advanced clinical N1/N2 lymphatic metastasis." (PMID 28225775, 2017).
Motor delay (1 paper, 2025). A type of Developmental delay characterized by a delay in acquiring motor skills. "Haploinsufficiency of BCL11A and BCL11B has been implicated in the development of NDDs, including ID, developmental speech delay, motor delay, and ASD." (PMID 40124112, 2025).
Nephropathy (1 paper, 2024). A nonspecific term referring to disease or damage of the kidneys. "Polymorphisms in genes such as BCL11A and HBS1L-MYB have been identified as key regulators of HbF production, offering potential targets for therapeutic modulation and personalized management of nephropathy in SCD patients." (PMID 38791464, 2024).
osteosarcoma (1 paper, 2006). A usually aggressive malignant bone-forming mesenchymal neoplasm, predominantly affecting adolescents and young adults. "Accordingly, we observed under transcriptional starvation and following cell damage with etoposide that BCL11A-XL and BCL6 re-localized to nucleoli in U2OS osteosarcoma cells (data not shown)." (PMID 16704730, 2006).
pancreatic cancer (1 paper, 2025). "BCL11A has also been identified as a possible prognostic marker for pancreatic cancer, as it has been linked to poorer overall survival." (PMID 41281751, 2025).
psoriasis (1 paper, 2022). An autoimmune condition characterized by red, well-delineated plaques with silvery scales that are usually on the extensor surfaces and scalp. "Additionally, a BCL11A genetic knockout model would be beneficial to future studies of psoriasis due to the implication of BCL11A in epidermal barrier impairment." (PMID 35214050, 2022).
pulpitis (1 paper, 2025). Inflammation of the dental pulp. "For the phenotype Pulpal and apical diseases, two other loci in chromosomes 2 (near BCL11A) and 9 (near RMI1), and for the phenotype Pulpitis, three other loci in chromosomes 1 (near PDE4B), 9 (near NR4A3), and 17 (near VMP1 and TUBD1) were identified." (PMID 40701953, 2025).
sarcopenia (1 paper, 2023). Progressive decline in muscle mass due to aging which results in decreased functional capacity of muscles. "Among the four DETFs, only PAX5 exhibited significantly decreased expression, while TP73, BCL11A and TFAP2C were increased in sarcopenia." (PMID 37525094, 2023).
Speech apraxia (1 paper, 2019). A type of apraxia that is characterized by difficulty or inability to execute speech movements because of problems with coordination and motor problems, leading to incorrect articulation. "Recently, point mutations that disrupt BCL11A function have been implicated in a neurodevelopmental syndrome that includes language delays, although a diagnosis of speech apraxia was not specifically reported in these cases." (PMID 29463886, 2019). "Still, the majority of speech apraxia cases do not seem to carry causal mutations in FOXP2, BCL11A or ERC1." (PMID 29463886, 2019).
squamous carcinoma (1 paper, 2013). "Furthermore, when BCL11A expression was analysed according to different histological subtypes, BCL11A mRNA was upregulated mainly in squamous cell carcinoma (SCC)." (PMID 23758992, 2013). "BCL11A protein was an independent prognostic factor of disease-free survival and overall survival for early stage patients (IA–IIB), especially for early stage squamous carcinoma patients." (PMID 23758992, 2013).
tumor (48 papers, 2004 to 2025). "In vitro and in vivo studies showed that silencing of BCL11A inhibited the tumorigenic potential of TN cell lines and caused tumor regression." (PMID 37185699, 2023). "SOX9- and BCL11A-encoded proteins were both involved in inducing tumor initiation, proliferation, migration, and chemoresistance." (PMID 36092919, 2022). "There is little research on BCL11A genotype polymorphisms, which have been described as related to certain other tumours." (PMID 28225775, 2017). "The proto-oncogene BCL11A spans over 102 kb on chromosome 2p16 and is implicated in several neoplasms." (PMID 23758992, 2013). "Higher levels of BCL11A were associated with tumor growth and shorter survival." (PMID 37372998, 2023). "Deletion of Bcl11a caused a significant reduction in tumour size as soon as 5 days post deletion." (PMID 25574598, 2015). "Chromatin remodeler CHD8 is a tumour-specific, targetable protein–protein interaction of the oncogenic transcription factor BCL11A in TNBC." (PMID 40328966, 2025). "We have previously reported the finding of one such gene, BCL11A, which is overexpressed in the majority of TNBCs and promotes tumour formation making it an attractive target for the treatment of TNBC tumours." (PMID 40328966, 2025). "In turn, high expression of BCL11A promoted tumor formation and correlated positively with the grade of histological malignancy, clinical stage and Ki-67." (PMID 37185699, 2023). "The analysis of BCL11A expression also showed a statistically significant inverse relationship with the primary tumor size (* p = 0.048) and the tumor size in cm (r = −0.34, *** p < 0.0001)." (PMID 37185699, 2023). "Recently, there has been research suggesting a link between high BCL11A expression and tumor resistance to tamoxifen therapy." (PMID 37185699, 2023). "It was reported that BCL11A has a potential role in tumor proliferation and metastasis through the Wnt/β-catenin signaling pathway in BRCA." (PMID 37007972, 2023). "We compared the transcriptome data between normal samples and GBM tumor samples, which indicated that ANXA1, PDPN, COL6A1, BCL3, RUNX1, and WWTR1 were upregulated and compared to normal samples, BCL11A was downregulated in GBM tumor samples." (PMID 37434432, 2023). "The inverse relationship between BCL11A expression and the grade of malignancy (G) is consistent with a significant negative correlation between the expression of this protein and the tumor size that we demonstrated in our study." (PMID 37185699, 2023). "High mutation frequencies were detected including KMT2C (5/5), MST1 (5/5), HLA-A (3/5) and BCL11A (3/5), which involved in modifications, tumor suppression and immune surveillance." (PMID 35504960, 2022). "As shown in Fig. (2A), NB patients with high expression of BCL11A in tumor tissues had significantly poorer OS than those with low expression (p=0.010)." (PMID 35909289, 2022). "Among the 53 patients, 17 (32.1%) cases developed tumor progression or recurrence and 12 of them were defined as having high expression of BCL11A." (PMID 35909289, 2022). "The differences in BCL11A between various tumor tissues and the matched normal tissues were analyzed using previously published microarray gene expression datasets." (PMID 35909289, 2022). "These genes were KMT2C, MST1, HLA-A and BCL11A which are involved in epigenetic modifications, tumor suppression and immune surveillance." (PMID 35504960, 2022). "Each tumor was assigned a BCL11A and MDM2 expression score based on the staining intensity and staining extent." (PMID 32266150, 2020). "These in vivo results demonstrate that BCL11A has important functions for LSCC in vivo tumor development." (PMID 32266150, 2020).